HP (haptoglobin)
Diseases named in the same sentence as HP in open-access papers (continued):
Sharing a sentence is not in itself a finding about the gene and the disease.
septic shock (4 papers, 2018 to 2025). Shock caused by infection; frequently caused by gram negative bacteria, although some cases have been caused by other bacteria, viruses, fungi, and protozoa; characterized by fever, chills, tachycardia, tachypnea, and hypotension. "In a study of septic shock patients, improved ICU mortality was linked to the concentration of haptoglobin in plasma; i.e., for patients with plasma haptoglobin <0.95 g/L, the mortality was 51%, while a higher concentration of haptoglobin was associated with a mortality of 34%." (PMID 40429487, 2025). "Quantitative Reverse Transcription Polymerase Chain Reaction validation was conducted for MMP8, MMP9, ARG1, HP, and CD163 across healthy controls, SIRS, and septic shock patient groups." (PMID 39560539, 2024).
Spherocytosis (4 papers, 2015 to 2025). The presence of erythrocytes that are sphere-shaped. "There were likely components of both intravascular and extravascular hemolysis given the laboratory findings of undetectable haptoglobin, spherocytosis on peripheral blood smear, and increased urine urobilinogen and urine blood without red blood cells." (PMID 39883062, 2025). "Guidance in China and Japan also includes low haptoglobin, and South Korea includes spherocytosis." (PMID 41210898, 2025).
acute respiratory distress syndrome (3 papers, 2021 to 2025). Progressive and life-threatening pulmonary distress in the absence of an underlying pulmonary condition, usually following major trauma or surgery. "In summary, LPS activated immune cytokines (IL-1B, IL6), induced the expression of HP, and further induced acute inflammatory response, and then caused the Acute respiratory distress syndrome." (PMID 34519633, 2021). "We evaluated the association of CFH and haptoglobin with AKI in patients with an acute respiratory distress syndrome (ARDS) requiring therapy with VV ECMO." (PMID 35193645, 2022).
amyloidosis (3 papers, 2015 to 2021). A disorder characterized by the localized or diffuse accumulation of amyloid protein in various anatomic sites. "We discovered, using a differential proteomics approach, that extracellular chaperones such as fibrinogen, clusterin, haptoglobin, alpha-1-anti-trypsin and 2-macroglobulin are overrepresented in transthyretin amyloidosis." (PMID 26147092, 2015). "In contrast, HP (as a major APP) was increased in 88% of cows with amyloidosis." (PMID 33996975, 2021).
Arthritis (3 papers, 2017 to 2022). Inflammation of a joint. "Previous studies have shown a serum haptoglobin response in horses with experimental arthritis, acute abdominal pain and transportation stress." (PMID 28629364, 2017). "Studies have shown that locally expressed HP promotes cell migration in cartilage and therefore may play a role in the progression of arthritis." (PMID 35603148, 2022). "Previous studies have shown that serum haptoglobin levels increase during arthritis." (PMID 35603148, 2022). "Very little is known about the haptoglobin response in inflammatory joint disease in horses and other species, but a recent study demonstrated increased concentrations of haptoglobin in SF obtained from horses 15 days after experimental induction of arthritis by IA injection of amphotericin B." (PMID 28629364, 2017).
atrophic gastritis (3 papers, 2022 to 2025). "Fifty-two participants were BR+, of whom 30 were male, 23 were HP-positive, and 23 had gastric atrophy, while 40 participants were BR-, of whom 19 were male, 15 were HP-positive, and 20 had gastric atrophy study." (PMID 36159635, 2022).
babesiosis (3 papers, 2014 to 2019). Babesiosis refers to a condition caused by microscopic parasites that infect the red blood cells. "Haptoglobin, and acute phase protein, also appeard among 21 proteins identified in the urine of dogs with babesiosis." (PMID 31801572, 2019). "Although it was not included in the final network of close connections selected by the Panther system, haptoglobin is considered to be one of the valuable markers used in the assessment of the course of babesiosis in dogs." (PMID 31801572, 2019). "Some authors found increase and some decrease of haptoglobin during babesiosis suggesting that serum concentration of Hp can be influenced by other factors than acute phase response." (PMID 24885808, 2014). "Three APP involved in haemoglobin and iron metabolism and transport, haptoglobin, hemopexin and serotransferrin, indicate the role of haemolysis in the course of babesiosis." (PMID 24885808, 2014). "Levels of CRP and haptoglobin were determined on day 0, day 1 and day 6 in serum of dogs with babesiosis and healthy dogs." (PMID 24885808, 2014). "The role of haemolysis in the course of babesiosis was demonstrated by haptoglobin, hemopexin and serotransferrin expression changes." (PMID 24885808, 2014). "We determined levels of haptoglobin in serum of all dogs, in order to achieve better understanding of haemolysis in babesiosis." (PMID 24885808, 2014). "Haptoglobin was identified only in dogs with babesiosis on 6th day after treatment." (PMID 24885808, 2014).
beta thalassemia (3 papers, 2015 to 2025). Beta-thalassemia (BT) is characterized by deficiency (Beta+) or absence (Beta0) of synthesis of the beta globin chains of hemoglobin (Hb). "The haptoglobin (Hp) 2-2 genotype is a significant predictor of premature atherosclerosis and is associated with increased CIMT in children with beta-thalassemia major." (PMID 26666335, 2015). "Beta-thalassemia children;study of serum haptoglobin and itsrelation to erythropoietic activity." (PMID 41281279, 2025).
chronic hepatitis (3 papers, 2018 to 2023). An active inflammatory process affecting the liver for more than six months. "We previously reported that serum fucosylated haptoglobin (Fuc-Hp) levels increase as the disease progresses from chronic hepatitis to cirrhosis and then HCC." (PMID 36542633, 2022). "Spot 1440 showed a 3.18-fold increase in abundance (for chronic hepatitis dogs compared to healthy control dogs; q = 0.00095) and contained annexin 5, regucalin, and haptoglobin." (PMID 30500850, 2018). "Among the various proteins, differently abundant fecal fibronectin and haptoglobin were more present in the feces of healthy and DHD dogs than in chronic ones, leading us to hypothesize its possible diagnostic/monitoring role in canine chronic hepatitis." (PMID 37508119, 2023). "Fecal fibronectin and haptoglobin were more present in the feces of healthy and DHD dogs than in chronic ones, leading us to hypothesize its possible diagnostic/monitoring role, to be confirmed with western blotting and in further studies in canine chronic hepatitis." (PMID 37508119, 2023).
chronic pancreatitis (3 papers, 2011 to 2018). A chronic inflammatory process causing damage and fibrosis of the pancreatic parenchyma. "In particular, increased sLex expression on α1-acid glycoprotein occurs in both cancer and chronic pancreatitis, while increased expression on haptoglobin, fetuin, antitrypsin and transferrin is associated only with chronic pancreatitis, not with pancreatic cancer." (PMID 28241499, 2017). "Of these, 118 (36%) were proven false positives of FT, due to 1) low haptoglobin in 114 (mostly hemolysis); 2) high GGT in two (chronic pancreatitis); and 3) low ApoA1 in two (severe undernutrition)." (PMID 21492460, 2011).
congestive heart failure (3 papers, 2009 to 2023). Failure of the heart to pump a sufficient amount of blood to meet the needs of the body tissues, resulting in tissue congestion and edema. "Haptoglobin increases after MI and elevated haptoglobin is a known risk factor for MI and congestive heart failure." (PMID 36197585, 2023).
duodenal ulcer (3 papers, 2016 to 2023). An ulcer in the duodenal wall. "In our study, duodenal ulcer was detected in 12 (57.1%) of 21 patients with ectopic gastric mucosa, and HP positivity was observed in 13 (61.9%) of them." (PMID 37061587, 2023).
enteritis (3 papers, 2013 to 2015). Inflammation of the small intestine. "Administration of warfarin failed to prevent recurrence of the abdominal pain and underlying enteritis while serum LDH and haptoglobin profiles indicated hemolytic anemia." (PMID 24587926, 2014).
gastric ulcer (3 papers, 2021 to 2022). An ulcerated lesion in the mucosal surface of the stomach. "The inflammatory response at the site of the ulcers is the main stimulus that increases the haptoglobin synthesis rate in the gastric ulcer." (PMID 34405561, 2021).
hematoma (3 papers, 2018 to 2023). A hematoma is a collection of blood from a vascular structure into an extravascular space. "Haptoglobin-Hb-CD163 as well as hemopexin-heme-LRP1 (low-density lipoprotein receptor-related protein-1) is believed to be the most important endogenous scavenging pathway which participates in hematoma/blood component resolution following ICH." (PMID 30123388, 2018). "Therefore, humanized anti-HMGB1 mAb could neutralize HMGB1 and liberate an abundant amount of haptoglobin to increase the clearance of Hb from hematoma clots." (PMID 36230933, 2022). "It has also been pointed out that the PPAR-γ agonist monascin increases the levels of haptoglobin (Hp) and CD163 on the surface of phagocytes in plasma, accelerating hematoma absorption through the Hp–Hb–CD163 pathway." (PMID 36970539, 2023).
hyperlipidemia (3 papers, 2020 to 2023). "Given that the only parental lifespan signal supported by GWAS, TWAS and proteome‐wide MR was at HP, the gene encoding haptoglobin (Hp), and that variation at the HP locus was linked with hyperlipidemia, we investigated genetic colocalization across multiple traits at the HP locus." (PMID 34704651, 2021).
Hypoalbuminemia (3 papers, 2019 to 2024). The concentration of albumin in the blood circulation is below the lower limit of normal. "Haptoglobin and ceruloplasmin increased as acute phase reaction proteins; alpha-2 macroglobulin increased in a compensatory manner to maintain plasma colloid osmotic pressure due to hypoalbuminemia." (PMID 31357953, 2019).
Hypocalcemia (3 papers, 2022 to 2025). An abnormally decreased calcium concentration in the blood. "Differential expression of proteins implicated in acute phase responses, coagulation, and inflammation, such as SAA, haptoglobin, fibrinogen, cadherin, and periostin, has been observed in periparturient cows exhibiting subclinical hypocalcemia or early-stage milk fever." (PMID 40284849, 2025). "Importantly, serum TNF-α, SAA, haptoglobin, and lactate were already increased at −8 and −4 weeks prior to parturition, suggesting that systemic inflammation may precede and contribute to the development of hypocalcemia." (PMID 40284849, 2025).
iron overload (3 papers, 2009 to 2025). "We also found exonic non-synonymous variants in BMP6, HP and Serpina1, whose proteins might act as possible modulators of hepcidin synthesis and iron overload." (PMID 33513852, 2021). "Present research suggested that altered expressions of HAMP, HP and A2M genes might have contributed to induce iron overload in PCOS patients." (PMID 40057801, 2025). "Moreover, haptoglobin protein binds to hemoglobin more effectively, hence decreased levels of plasma HP may depict the excessive availability of free hemoglobin and subsequently leading to iron overload." (PMID 40057801, 2025).
lymphoma (3 papers, 2016 to 2025). A malignant (clonal) proliferation of B- lymphocytes or T- lymphocytes which involves the lymph nodes, bone marrow and/or extranodal sites. "In cancer, the upregulation of haptoglobin has been associated with poor prognosis, particularly in haematological malignancies such as lymphoma and leukaemia." (PMID 40606553, 2025). "C-reactive protein, thymidine kinase 1, and haptoglobin have been most extensively studied and commercialized in diagnostic tests, the TK Canine Cancer Panel and the Canine Lymphoma Blood Test." (PMID 27747218, 2016). "Elevated levels of haptoglobin are commonly observed in various malignancies, including lymphoma, leukaemia, and solid tumours such as breast, prostate, and colorectal cancers." (PMID 40606553, 2025). "Haptoglobin’s role extends to pathological conditions such as lymphoma and leukaemia, where its expression and function are altered due to disease progression." (PMID 40606553, 2025). "For example, in lymphoma and leukaemia, high levels of haptoglobin correlate with poor prognosis, potentially due to its role in suppressing anti-tumour immune responses and fostering an immunosuppressive environment." (PMID 40606553, 2025). "Increased serum haptoglobin levels have been observed in various cancers, including lymphoma and leukaemia, reflecting its role in the tumour microenvironment." (PMID 40606553, 2025). "Measurement of fucosylated serum proteins as well as SAA, CRP, and haptoglobin has been evaluated as biomarkers of lymphoma disease and treatment monitoring." (PMID 27747218, 2016). "Using a surface-enhanced laser desorption ionization time of flight (SELDI-TOF) protein detection method, another group identified CRP and haptoglobin as potential biomarkers of lymphoma and created ELISA-based assays for those proteins." (PMID 27747218, 2016). "In another study, haptoglobin (Hp), α2 macroglobulin, α-antichymotrypsin, inter-α-trypsin inhibitor, and clusterin were identified in dog sera with a lymphoma versus a non-lymphoma group by two-dimensional electrophoresis (2DE) and tandem MS." (PMID 35765478, 2022). "Six candidate increased proteins in canine lymphomas were beta-actin cytoplasmic 1 (ACTB, p=0.04), haptoglobin (p=0.002), beta-2 microglobulin (aaaaaaaa2M, p=0.007), beta-2 glycoprotein 1 (APOH, p=0.03), metalloproteinase inhibitor 1 (TIMP-1, p=0.03), and CD44 antigen (p=0.02)." (PMID 35765478, 2022).
malnutrition (3 papers, 2024). Inadequate nutrition resulting from poor diet, malabsorption, or abnormal nutrient distribution. "For example, reduced concentrations of haptoglobin are observed in conditions other than hemolysis, such as liver impairment or malnutrition." (PMID 38665872, 2024). "Reasons for decreased haptoglobin levels may be hemolysis, allergic reactions or malnutrition." (PMID 38254757, 2024).
Miscarriage (3 papers, 2010 to 2019). A pregnancy that ends at a stage in which the fetus is incapable of surviving on its own, defined as the spontaneous loss of a fetus before the 22th week of pregnancy. "In conclusion the results of this study suggest that Obese and overweight women with recurrent miscarriage have an altered endometrial protein profile that is mainly related to changes in haptoglobin expression." (PMID 25096020, 2014). "Obese and overweight recurrent miscarriage patients had a significantly increased endometrial expression of haptoglobin compared to their lean counterparts (p = 0.01)." (PMID 25096020, 2014). "Haptoglobin therefore seems to be affected both by the presence of recurrent miscarriage as well as by increased BMI, as both conditions seem to have an opposite effect on haptoglobin concentrations." (PMID 25096020, 2014). "However, in Group D women the increased expression of HP suggests that the “stress test” of a female during pregnancy resulting in miscarriage may have left some inflammatory signatures, where increasing expression of HP remains one facet." (PMID 30783564, 2019). "Networking analyses suggest cross talk between the four dysregulated proteins, that is, HP, TF, ApoA1, and TTR as a connecting link between miscarriage history and MeS." (PMID 30783564, 2019). "Increased expression of TF, HP protein (three isoforms), SYNE 1, serpin 38, and ApoA1 in groups A, C, and D provides a better insights into the molecular link between the history of miscarriage and MeS." (PMID 30783564, 2019).
pancreatitis (3 papers, 2017 to 2026). Inflammation of the pancreas. "Our findings did not support the practical usefulness of hepcidins or haptoglobin in tracking pancreatitis in dogs." (PMID 41807952, 2026).
thalassemia (3 papers, 2008 to 2024). An inherited blood disorder characterized by a decreased synthesis of one of the polypeptide chains that form hemoglobin. "The haptoglobin HP2-2 genotype has been associated with idiopathic generalized epilepsies and altered iron metabolism in children with α-thalassaemia can potentially interfere with neurotransmission and increase the risk of seizures." (PMID 18554871, 2008). "In 267 out 288 (92.7%) children, both the haptoglobin genotype and α-thalassaemia type was available and the cases and controls could be matched for ethnicity." (PMID 18554871, 2008). "For coping with oxidative stress, nonenzymatic defense mechanisms encompassing metal-binding proteins (such as haptoglobin and albumin) and free radical scavengers like serum UA are required to maintain redox homeostasis, which is disturbed in diseases affecting iron metabolism, such as thalassemia." (PMID 38255787, 2024).
thyroid cancer (3 papers, 2009 to 2018). "We explored the risk of developing a thyroid cancer by assessing serum biomarkers that are commonly measured in clinical practice and are indicative of inflammation (CRP, albumin, haptoglobin and leukocytes) in a large Swedish cohort study." (PMID 29416653, 2018).
trypanosomiasis (3 papers, 2014 to 2017). Infection with protozoa of the genus trypanosoma. "From these genes, only haptoglobin (HP) at the SNP rs8062041 was found to have polymorphisms which were strongly associated with trypanosomiasis." (PMID 29077717, 2017).
tuberculosis (3 papers, 2012 to 2022). A chronic, recurrent infection caused by the bacterium Mycobacterium tuberculosis. "A meta-analysis performed with 16 microarray datasets to profile the host transcriptional response in active tuberculosis led to the identification of five upregulated genes: AIM2, BATF2, FCGR1B, HP, and TLR5." (PMID 35456421, 2022).
acute respiratory failure (2 papers, 2011 to 2025). Life-threatening respiratory failure that develops rapidly. "In this study, we investigated the incidence of hemolysis, reflected by decreased haptoglobin and hemopexin levels, in septic patients with acute respiratory failure admitted to the ICU." (PMID 40429487, 2025). "Although serum haptoglobin levels can be increased in inflammatory conditions, of the two patients in our study who were admitted with acute respiratory failure neither was noted to have abnormally elevated baseline serum haptoglobin levels." (PMID 21860624, 2011). "In our study, a prediction model for mortality was developed, with a haptoglobin level below 0.30 g/L, advanced age, and a diagnosis of AKI stage 3 remaining independent predictors of mortality in the population of septic patients with acute respiratory failure." (PMID 40429487, 2025).
alcohol dependence (2 papers, 2020 to 2023). Physical and psychological dependence on alcohol. "Other salivary glycoproteins, such as α-amylase, clusterin, haptoglobin, and light and heavy chain immunoglobulin, identified as potential markers of alcohol dependence need further direct research, based on a larger sample." (PMID 33334005, 2020).
Bovine mastitis (2 papers, 2020 to 2025). INFLAMMATION of the UDDER in cows. "Moreover, serum amyloid A (SAA) and haptoglobin (Hpt) are important markers for the determination of bovine mastitis." (PMID 40105325, 2025).